METTL3 (methyltransferase 3, N6-adenosine-methyltransferase complex catalytic subunit)
Diseases named in the same sentence as METTL3 in open-access papers (continued):
Sharing a sentence is not in itself a finding about the gene and the disease.
liver cancer (continued). "METTL3, a key catalytic subunit of m6A modification, has been shown to play an important role in liver cancer regulation." (PMID 40097750, 2025). "METTL3 mediates MiR‐589‐5p maturation and expression, which is positively correlated and over-expression can promote the deterioration of liver cancer." (PMID 41256854, 2025). "Previous reports have indicated the involvement of both METTL3 and c-Src kinase in the evolution of liver cancer." (PMID 40612868, 2025). "Together, our results showed a critical role of the IRF1/c-Src axis in the METTL3-promoted liver cancer progression." (PMID 40612868, 2025). "Results found that METTL3 was upregulated in tumor tissues and liver cancer cell lines, and it was positively correlated with BFSP1 expression." (PMID 40097750, 2025). "The functional roles of c-Src in METTL3-regulated liver cancer progression were investigated by cell proliferation assays and colony formation assays." (PMID 40612868, 2025). "METTL3 also increases lenvatinib resistance in liver cancer by regulating frizzled class receptor 10 (FZD10) m6A modification, activating the β‐catenin and YAP1 pathways." (PMID 39802639, 2025). "The correlation expression between c-Src and METTL3 between liver cancer patients and the control group was analyzed using the TCGA database, and was further demonstrated by Western blot and RT-qPCR." (PMID 40612868, 2025). "In summary, METTL3 accelerated the malignant progression and lung metastasis of liver cancer by upregulating BFSP1 expression." (PMID 40097750, 2025). "In summary, we showed that METTL3/IRF1/c-Src axis played oncogenic roles in the development of liver cancer." (PMID 40612868, 2025). "We further confirmed that the IRF1/c-Src axis promoted the METTL3-regulated proliferation of liver cancer cells." (PMID 40612868, 2025). "Last, we proved that the upregulation of IRF1/c-Src expression participated in the METTL3-promoted cell proliferation of liver cancer." (PMID 40612868, 2025). "We further provided evidence showing that IRF1 was a novel transcription factor of SRC, and the IRF1/c-Src axis participated in METTL3-promoted proliferation of liver cancer cells." (PMID 40612868, 2025). "Research hasfound that METTL3 promotes the invasion and proliferation of liver cancer cells by inducing m6A modification of target genes." (PMID 40097750, 2025). "Together, these data suggested that SRC mRNA can be m6A modified via METTL3, and METTL3 upregulated the expression of c-Src in liver cancer cells." (PMID 40612868, 2025). "This study found that METTL3 was upregulated in liver cancer and facilitated the malignant phenotype of cancer cells by promoting m6A methylation of BFSP1 mRNA." (PMID 40097750, 2025). "METTL3 promotes the proliferation and stemness of liver cancer stem cells (LCSCs) by targeting SOCS3 mRNA through the JAK2/STAT3 pathway." (PMID 41256854, 2025). "In the context of liver cancer progression, single-cell RNA sequencing has illuminated the pivotal role of METTL3, a key m6A writer, in modulating the immune microenvironment." (PMID 39911396, 2025). "In this study, we bridged the association between SRC and METTL3 according to publicly available liver cancer datasets with clinical data and functional analyses revealed that METTL3 modulates SRC mRNA expression through m6A-dependent mechanisms." (PMID 40612868, 2025). "Here, we found that METTL3 induces aerobic glycolysis in liver cancer by upregulating m6A modification of BFSP1, which can be achieved by recruiting YTHDF1." (PMID 40097750, 2025). "Clinical data analysis showed a positive correlation between both METTL3/SRC and METTL3/IRF1, as well as the OS of liver cancer patients associated with METTL3/SRC expression." (PMID 40612868, 2025). "According to GEPIA2 analysis, there was a significant positive correlation between SRC and METTL3 expression in liver cancer tissues was observed (r = 0.41; p = 4.40 × 10−16)." (PMID 40612868, 2025).
liver cancer (continued). "METTL3 is overexpressed in colorectal, gastric, and liver cancers, promoting cancer cell proliferation by inhibiting the tumor suppressor SOCS2." (PMID 39473440, 2024). "At present, the relationship between Mettl3 and Mettl14 and liver cancer and the exact mechanism still need to be further studied." (PMID 38166832, 2024). "In liver cancer, METTL3 participates in RNA decay by facilitating the binding of m6A reader YTHDF2 to the SOCS2 gene, ultimately promoting cancer cell proliferation and migration." (PMID 38966069, 2024). "In turn, the frizzled 10-β-catenin/c-Jun axis also transcriptionally activates METTL3 expression, forming a positive feedback loop that promotes self-renewal, expansion of liver cancer stem cells, and metastasis of liver cancer cells." (PMID 38856795, 2024). "Consistent with previous research, we found that METTL3 was significantly upregulated in liver cancer tissues." (PMID 39695152, 2024). "When we performed survival analysis using METTL3 and METTL14 as a gene set, we found that METTL3 and METTL14 contributed completely opposite prognostic risk values in liver cancer." (PMID 38965238, 2024). "We next used RM2Target to find potential targets of METTL3 and its m6A effector in liver cancer to provide candidates for further functional and mechanism studies." (PMID 36300630, 2023). "The experimental data support the potential of METTL3 as a biomarker and therapeutic target in liver cancer." (PMID 38012755, 2023). "METTL3 has carcinogenic function in human liver cancer, and downregulation of METTL3 can weaken the tumorigenicity and lung metastasis of liver cancer." (PMID 37519297, 2023). "In the orthotopic liver transplantation model, knockdown of METTL3 can reduce the occurrence of liver cancer and lung metastasis." (PMID 37170222, 2023). "Significantly, experimental studies were conducted, confirming the high expression of METTL3 in liver cancer clinical tissues and cell lines." (PMID 38012755, 2023). "Interfering with METTL3 expression can reduce the level of m6A modification of HIF1α and inhibit the metabolic reprogramming of colorectal and liver cancer cells." (PMID 36855123, 2023). "In summary, this study found that METTL3‐mediated maturation of miR‐589‐5p promoted the malignant development of liver cancer." (PMID 35348293, 2022). "After transfection, the viability, migration, invasion and expressions of METTL3 and miR‐589‐5p in liver cancer cells were detected by CCK‐8, wound‐healing, transwell and RT‐qPCR." (PMID 35348293, 2022). "Our research revealed that METTL3‐mediated m6A modification promoted the maturation of miR‐589‐5p and the malignant development of liver cancer." (PMID 35348293, 2022). "Overexpressed miR‐589‐5p and METTL3 promoted the viability, migration and invasion of liver cancer cells, while the effects of silencing miR‐589‐5p and METTL3 on the cells were the opposite." (PMID 35348293, 2022). "Given that the important role of hypoxia in tumor development, our research group has long focused on the role of hypoxia in liver cancer, and METTL3 YTHDF2 and METTL14 has been studied more frequently in liver cancer." (PMID 35982895, 2022). "Meanwhile, as compared with the normal cells, liver cancer cells showed a high level of METTL3 (p < 0.001), indicating that METTL3 had a regulatory effect on liver cancer." (PMID 35348293, 2022). "Such as, METTL3 promotes liver cancer progression by regulating SOCS2 in an YTHDF2-dependent manner." (PMID 36008805, 2022). "METTL3 affects FOXO3 RNA stability in a YTHDF1-dependent manner to inhibit the expression of FOXO3 to inhibit autophagy; The reduced expression of METTL3 increases the number of autophagosomes to activate autophagy in liver cancer cells." (PMID 35141221, 2022). "METTL3 knockdown decreased RNA m6A modification and proliferation in pancreatic and liver cancer cells." (PMID 35571106, 2022).
liver cancer (continued). "For instance, METTL3 promotes liver cancer progression via regulating SOCS2 expression in an m6A-dependent manner." (PMID 36008805, 2022). "METTL3 was reported to promote liver cancer progression; mechanistically, METTL3 increased SOCS2 mRNA m6A abundance, leading to SOCS2 mRNA degradation, which was mediated by YTHDF2." (PMID 36009465, 2022). "METTL3 regulates β-catenin protein expression and membrane localisation in cervical, lung, and liver cancers, thereby promoting cell migration, invasion, and EMT." (PMID 36358640, 2022). "We found that METTL3 overexpression promoted the viability, migration and invasion of liver cancer cells, and that METTL3 silencing further inhibited the growth of xenografted‐tumour in nude mice but the effects of miR‐589‐5p mimic were the opposite." (PMID 35348293, 2022). "Research shows that METTL3 promotes cancer progression through YTHDF2 dependent posttranscriptional silencing of SOCS2 in liver cancer." (PMID 35595748, 2022). "METTL3 has been shown to be significantly overexpressed in lung cancer, liver cancer and GC, and involved in regulating tumor progression." (PMID 35742899, 2022). "Our research, for the first time, verified that METTL3 promoted the maturation of miR‐589‐5p via enhancing m6A modification of pri‐miR‐589 and further enhanced the malignant development of liver cancer." (PMID 35348293, 2022). "It was demonstrated that suppressor of cytokine signaling 2 was the target of METTL3-mediated m6A modification and METTL3 repressed its expression through an m6A-YTHDF2-dependent pathway in liver cancer." (PMID 35280730, 2022). "In a mouse xenograft model, METTL3 deletion significantly enhanced the resistance of liver cancer to sorafenib by disrupting the METTL3-mediated stability of FOXO3 mRNA, while FOXO3 overexpression restored the sensitivity of liver tumours to sorafenib." (PMID 34246319, 2021). "METTL3 is also a tumor suppressor—it promotes the occurrence and development of liver cancer by reducing the stability of SOCS2 mRNA through m6A-YTHDF2-dependent pathways." (PMID 33540684, 2021). "In human liver cancer, the circRNA CircMEG3 inhibits the growth of the liver cancer stem cells repressing the expression of the m6A methyltransferase METTL3 and Cbf5, which in turn represses the telomerase activity." (PMID 34439740, 2021). "Previous work showed that the m6A methylase METTL3 is significantly upregulated in human liver cancer and other malignancies, and that its high expression predicts poor clinical prognosis." (PMID 34497267, 2021). "This is consistent with the results of previous studies suggesting that the overexpression of METTL3 often indicates poor prognosis in patients with primary liver cancer." (PMID 33643384, 2021). "Recent research showed that METTL3 is involved in liver cancer development by regulating the proliferation and differentiation of liver cells via inducing SOCS2 mRNA m6A modification." (PMID 34616359, 2021). "It was found that the expression of METTL3‐induced lncRNAs ABHD11‐AS1 and LINC00958 was upregulated in non‐small‐cell lung cancer (NSCLC) and liver cancer tissues and cells and closely associated with the poor prognosis of patients." (PMID 34432955, 2021). "Collectively, these results showed that the mitogen-response SUMOylation of Mettl3 was positively correlated with high metastatic potential liver cancer, which was regulated by Snail." (PMID 32483411, 2020). "To investigate the possible regulatory role of Mettl3 SUMOylation in liver cancer, we examined mitogen-response SUMOylation of Mettl3 in MHCC97H cells." (PMID 32483411, 2020). "Mitogen-response SUMOylation of Mettl3 showed a positive correlation to high metastatic potential in liver cancer and regulated EMT progression by controlling Snail mRNA homeostasis via m6A methyltransferase activity." (PMID 32483411, 2020). "Next, we examined the effect of Mettl3 SUMOylation regulation of Snail- mediated liver cancer progression in vivo and in vitro." (PMID 32483411, 2020).
liver cancer (continued). "It confirmed that PDK4 was involved in Mettl3 regulated glycolysis of cervical and liver cancer cells." (PMID 32444598, 2020). "(d) HULC enhances the expression and maturity of miR675 dependent on METTL3 in human liver cancer liver cells." (PMID 31900225, 2020). "By analyzing the pathological stage plot in liver cancer in the TCGA database, we found that METTL3 expression level was significantly down‐regulated in advanced stages of HCCs." (PMID 32368828, 2020). "Furthermore, Mettl3 SUMOylation has been preliminary identified to enhance tumor growth in human non-small cell lung carcinoma cell line H1299 24, but the role of Mettl3 SUMOylation in liver cancer progression and the underlying regulatory mechanisms of tumorigenesis have yet to be elucidated." (PMID 32483411, 2020). "It suggested that PDK4 was involved in Mettl3 regulated growth and chemosensitivity of cervical and liver cancer cells." (PMID 32444598, 2020). "Liver cancer cells transfected with the empty vector, Mettl3-WT, or Mettl3-KR were extracted for the dot-blot assay." (PMID 32483411, 2020). "We demonstrated UBC9/SUMOylated Mettl3/Snail axis as a novel mediator of the SUMO pathway involved in liver cancer progression." (PMID 32483411, 2020). "Another study also proves that METTL3, a major RNA N6-adenosine methyltransferase, promotes liver cancer progression through YTHDF2 dependent post-transcriptional silencing of SOCS2." (PMID 30877265, 2019). "Chen and colleagues demonstrated that the expression of METTL3 in human liver cancer is frequently up-regulated and contributes to the progression of liver cancer." (PMID 31810483, 2019). "In addition, the expression of IRF1 was positively correlated to both SRC and METTL3 in liver cancer patients, p = 6.60 × 10−5 and p = 4.10 × 10−4, respectively." (PMID 40612868, 2025). "In addition, METTL3 promotes lung metastasis of liver cancer by promoting GBAP1 m6A modification to induce GBAP1 expression." (PMID 40097750, 2025). "In addition, METTL3 drives aerobic glycolysis in liver cancer cells by mediating target gene m6A modifications." (PMID 40097750, 2025). "This challenges the traditional view of METTL3 as an oncogene in liver cancer and suggests that its function may be context‐dependent." (PMID 40103332, 2025). "Here, we found that METTL3 was significantly positively correlated with YTHDF1 in liver cancer." (PMID 40097750, 2025). "However, the potential connection between c-Src and the METTL3-mediated mechanism in liver cancer progression remains elusive." (PMID 40612868, 2025). "Since IRF1 unaffected the OS of liver cancer patients and c-Src acts as an effector in the METTL3/IRF1/c-Src axis, we further overexpressed c-Src in sh-METTL3 Huh7 and siMETTL2 HepG2 cells, respectively, to confirm the oncogenic role of METTL3/IRF1/c-Src axis in liver cancer cell proliferation." (PMID 40612868, 2025). "In liver cancer, the relationship between METTL3 and c-Src has seldom been reported." (PMID 40612868, 2025). "Together, results indicated that METTL3 modulated the transcription of SRC in liver cancer cells." (PMID 40612868, 2025). "METTL3 has been shown to have oncogenic properties in liver cancer." (PMID 40451925, 2025). "Finally, although we established a link between METTL3 O-GlcNAcylation and the initiation of liver cancer, the extent of its influence on advanced HCC stages and its significance in the context of anti-cancer therapeutics remain to be determined." (PMID 40651967, 2025). "Furthermore, liver cancer patients with higher METTL3 expression showed poorer OS (p = 3.00 × 10−3)." (PMID 40612868, 2025). "Results suggested that the METTL3/IRF1/c-Src axis played potential oncogenic roles in liver cancer development and the axis may be a promising therapeutic target in the disease." (PMID 40612868, 2025). "Next, the potential linkage between SRC and METTL3 in liver cancer was investigated." (PMID 40612868, 2025).
liver cancer (continued). "METTL14 promotes SOCS2 expression to inhibit the progression of liver cancer, while METTL3 inhibits SOCS2 expression in a YTHDF2-dependent manner, but whether METTL3 regulates the metabolism of HCC through SOCS2 requires more direct evidence." (PMID 38560499, 2024). "In this study, we demonstrated that lncRNA TUG1 upregulation was mediated by METTL3‐mediated m6A modification and examined the underlying mechanism of how TUG1 in liver cancer cells regulates the antitumor response of CD8+ T cells and phagocytosis of macrophages." (PMID 38981064, 2024). "Hence, our study identifies the METTL3/SLC50A1 axis as a novel relevant therapeutic target in the context of liver cancer." (PMID 39695152, 2024). "In liver cancer, METTL3 can stabilize FOXO3 mRNA, reducing autophagy and sorafenib resistance." (PMID 37675218, 2023). "M6A methylase METTL3 has a carcinogenic function in human liver cancer." (PMID 37170222, 2023). "Here, we showed how to explore the function of METTL3 in liver cancer using RM2Target." (PMID 36300630, 2023). "METTL3 can stabilize SEC62 in liver cancer cells by m6a modification to promote cell proliferation." (PMID 37781524, 2023). "In vitro study showed that miR‐589‐5p and METTL3 were highly expressed in liver cancer." (PMID 35348293, 2022). "In addition, highly expressed METTL3 in clinical liver cancer samples was further verified (p < 0.001); moreover, the positive correlation of METTL3 and miR‐589‐5p expressions was also confirmed in liver cancer samples." (PMID 35348293, 2022). "In liver cancer, METTL3 depletion enhanced sorafenib resistance via METTL3/FOXO3 axis." (PMID 35351856, 2022). "Moreover, miR‐589‐5p mimic and inhibitor reversed the effects of METTL3 silencing and overexpression on liver cancer, indicating that METTL3/miR‐589‐5p enhanced the malignant development of liver cancer." (PMID 35348293, 2022). "METTL3, a m6A methyltransferase, is up-regulated in gastric, colorectal, and liver cancers." (PMID 35884552, 2022). "Moreover, METTL3 was also highly expressed in several cancers, including in liver cancer, and promoted the viability, migration and invasion of liver cancer cells, and METTL3 silencing further inhibited the growth of xenograft tumour in the nude mice." (PMID 35348293, 2022). "In addition, after silencing METTL3 in the two liver cancer cells, the expression of miR‐589‐5p was down‐regulated (p < 0.001)." (PMID 35348293, 2022). "In liver cancer, METTL3 and METTL14 play opposite roles in tumor development." (PMID 34489709, 2021). "METTL3 was significantly elevated and promoted the proliferation of tumor cells by suppressing the expression of the suppressor of the cytokine signaling 2 gene in colorectal and liver cancers." (PMID 34858499, 2021). "However, the regulatory role of posttranslational modifications of Mettl3 in liver cancer remains elusive." (PMID 32483411, 2020). "Additionally, in our immunofluorescent experiments, an overlapping signal (yellow) of Mettl3 (red) and SUMO1 (green) was observed in the cytoplasm and nucleus of liver cancer cells, indicating that Mettl3 can be conjugated to SUMO-1." (PMID 32483411, 2020). "However, the precise regulatory mechanisms by which posttranslational modifications of Mettl3 impact liver cancer EMT progression remain to be explored." (PMID 32483411, 2020). "Additionally, in vitro functional assays showed that siMettl3-mediated knockdown of Mettl3 decreased cell viability, while promoting apoptosis in liver cancer cells, suggesting that Mettl3 was involved in the progression of HCC." (PMID 32483411, 2020). "Moreover, our study indicated that mitogen stimulation enhanced SUMO1 conjugation of Mettl3, thus promoting liver cancer progression." (PMID 32483411, 2020). "Therefore, we performed in vitro functional studies to investigate the role of Mettl3 SUMOylation in liver cancer." (PMID 32483411, 2020). "In liver cancer, METTL3 is frequently upregulated in human HCC and contributes to HCC progression." (PMID 31670863, 2020).